VIM (vimentin)
Diseases named in the same sentence as VIM in open-access papers (continued):
Sharing a sentence is not in itself a finding about the gene and the disease.
tumor (continued). "This signaling increased the expression of EMT markers (fibronectin, N-cadherin, and vimentin) and promoted tumor cell invasion." (PMID 35328699, 2022). "Endothelial cells treated with NMU also change their phenotype, increase the production of IGFBP-7 and vimentin, markers of tumour endothelial cells (TECs), and become more motile with an increased ability to form capillaries." (PMID 36482448, 2022). "Our team also focused on classifying CRC based on IHC reactions and used markers of EMT such as E-cadherin, β- catenin, vimentin, and maspin, evaluated in both tumor center and invasion front/tumor buds." (PMID 36012726, 2022). "A significant correlation was detected between vimentin expression and poor histologic differentiation, finger-like invasive fronts, as well as marginally with lymph node involvement and stage of the tumor." (PMID 36321045, 2022). "Treatment of xenografted human CRC on the CAM with anti-vimentin antibodies inhibited both tumor growth and vascular density in the tumors, and resulted in increased necrosis." (PMID 35606362, 2022). "As expected, the expression of E-cadherin significantly decreased in tumor cells stimulated by high stiffness, while the expression of N-cadherin and Vimentin increased." (PMID 36355508, 2022). "This allows EMT transcription factors to promote expression of mesenchymal proteins including vimentin that confer the ability on tumor cells to cross tissue barriers." (PMID 35215208, 2022). "Under in vivo conditions, NaB promoted partial EMT process, featured by up-regulation of E-cadherin, N-cadherin, and vimentin in tumor tissues." (PMID 36338704, 2022). "It has been reported this fluorescent probe permits the Vimentin identification and facilitates the visualization and enrichment of active tumour initiating cells." (PMID 36566021, 2022). "Vimentin is highly expressed in a variety of tumors, which is closely related to promoting tumor growth, invasion, and poor prognosis." (PMID 35359350, 2022). "On immunohistochemical staining, tumor cells showed diffuse positivity for CK-pan, but focal for CK-7 and vimentin." (PMID 35086533, 2022). "To determine EMT features in different subsets of tumor cells, we examined the expression of vimentin, N-cadherin, and E-cadherin in human pNET tissues, by IHC, along with Periodic Acid-Schiff (PAS) double staining for the matrix." (PMID 36497140, 2022). "We began by collecting NAFs and CAFs from healthy paracancerous lung tissues and NSCLC tumours, respectively, with both cell populations exhibiting vimentin positivity and spindle‐like morphology." (PMID 35857905, 2022). "Collectively, vimentin has emerged as one of the drivers of the critical events and is widely regarded to be beneficial for tumor progression." (PMID 35207438, 2022). "Despite the effectiveness of IHC staining, a definitive diagnosis of EMC cannot be made solely from positive IHC results for CD117, vimentin, CD56 and NSE as specific markers; however, IHC provided a diagnostic clue, and NGS was performed on the tumor." (PMID 35488288, 2022). "Targeting vimentin induces a pro-inflammatory condition in the tumor, exemplified by induction of the endothelial adhesion molecule ICAM1, suppression of PD-L1, and altered immune cell profiles." (PMID 35606362, 2022). "Vaccination against vimentin resulted in reduced tumor growth explained by the induction of a robust vimentin-specific humoral response, altered expression of leukocyte adhesion molecules, and a notable switch in the intratumoral immune cell repertoire." (PMID 35606362, 2022).
tumor (continued). "Both the FGF2-neutralizing antibody and PD-166866 inhibited the expression levels of p-FGFR1 and FAPα in HSCs, suppressed the recruitment of Gr-1+ MDSCs, decreased the expression of vimentin, and increased the expression of E-cadherin in tumor cells." (PMID 35951441, 2022). "Owing to their relevance in mechanobiology and tumor progression, Vimentin IFs have become a popular target of super-resolution imaging." (PMID 35269626, 2022). "The downregulation of the cell adhesion protein E-cadherin and cytoskeletal rearrangements, including downregulation of keratin and upregulation of vimentin, are the main features of EMT, which cause ultimately tumor progression and metastasis." (PMID 36246561, 2022). "Our data showed that normal tissue-derived organoids exhibited some tumor-like features, so we explored the expression patterns of VIM and EPCAM in the epithelial cells from all patients." (PMID 35484598, 2022). "This study aimed to assess the potential use of the biodegradable adjuvant Montanide ISA 720 in combination with our vaccine against extracellular vimentin, a protein specifically secreted by the tumor vasculature." (PMID 35681575, 2022). "In colorectal cancer, AKT phosphorylation can activate the transcription factors SLUG, SNAIL1 and TWIST, leading to increased expression of vimentin and suppression of E-cadherin, which creates suitable conditions for tumor metastasis." (PMID 36003306, 2022). "Tumor cells tend to promote the expression levels of mesenchymal-related markers including Vimentin and Snail, as well as suppress the expression of epithelial-related genes including E-cadherin." (PMID 35208999, 2022). "In our study, the expression of the EMT marker vimentin dropped in 3D stroma-tumor spheroids with an increased tumorous component." (PMID 36552039, 2022). "In the equine HNSCCs analyzed, vimentin was expressed by tumor cells to a various extent in 100% of lesions, irrespective of the precise tumor location and the EcPV2 infection status." (PMID 35215208, 2022). "An immunohistochemical analysis was performed to determine the expression of phosphorylated-c-Met, proliferation indicator (Ki-67), and EMT markers (Vimentin and E-cadherin) in tumor tissues derived mice." (PMID 36291760, 2022). "αSMA+ fibroblasts were enriched in juxta-tumoral regions, while VIM+ fibroblasts were evenly distributed throughout the tumor stroma." (PMID 35618735, 2022). "Intracellular staining for vimentin has been suggested for distinguishing tumor cells from fibroblasts by IHC or flow cytometry." (PMID 35316296, 2022). "Immunohistochemically, the cells expressed vimentin and, especially in peri-genital tumours, were positive for smooth muscle actin; in 50% of the tumours, CD34 positivity and S-100 negativity were observed." (PMID 35906668, 2022). "Our data indicate that elevated expression of SCAND1 and MZF1 can reverse the hybrid EMT status of tumor cells to a more epithelial status, although vimentin and nuclear β-catenin remained, suggesting that the cells were not fully epithelial." (PMID 36552758, 2022). "As expected, Vimentin levels were too low in the tumor area, but localized around the metastatic site in all the samples studied and the staining was somewhat increased in Non-Skip N2 samples." (PMID 35201505, 2022). "On the other hand, the expression of E-cadherin was observed in HSC-2, but vimentin was undetectable, as expected for this tumor type." (PMID 34874922, 2022). "Vimentin at ITF was positive in 47.6% (50/105) of patients whose tumors showed an invasive tumor front." (PMID 35498535, 2022). "The expression characteristics of vimentin and N-cadherin play an important role in tumor metastasis and are commonly used to assess the migration ability of cells." (PMID 35440604, 2022).
tumor (continued). "Nonetheless, Lazarevic and colleagues reported higher expression of EMT markers, including vimentin, in primary cell cultures derived from surgically resected margins compared to those from the tumor tissues obtained from six patients with OSCC." (PMID 35207438, 2022). "Tumor immunohistochemical analyses were presented as follows: Inhibin-α (-), ER (-), Vimentin (mesenchyme +), CK7 (+), CK19 (+), CK20 (−), CEA (−), MUC-1 (+), MUC-5AC (+), MUC-6 (+), MUC-2 (−), S-100p (focal+), and Ki-67 (12% +)." (PMID 33592896, 2021). "We performed univariate analysis through the Cox models for demographic and clinico-pathological variables, and also for dichotomized biomarkers, i.e., PD-L1 and vimentin in tumor cells, both with 1 and 50% cutoffs." (PMID 34917615, 2021). "Expression of ITGA11 was negatively correlated with CDH1, whereas positively correlated with VIM or CDH2 in tumor samples of STAD from the TCGA and GSE66229 datasets." (PMID 34222028, 2021). "Subsequently, the expression of mesenchymal markers, that is vimentin, N‐cadherin and epithelial marker E‐cadherin in tumour tissues, was also measured by Western blot analysis." (PMID 33350586, 2021). "PD-L1 median percentage in tumor cells was equal to zero as well as the vimentin median percentage in tumor cells." (PMID 34917615, 2021). "They play a central role in controlling the migratory potential of tumor cells by regulating the epithelial-to-mesenchymal transition (EMT)-associated gene expression, such as Vimentin and E-cadherin, in response to either oxidative stress or DNA damage." (PMID 34572494, 2021). "In particular, we retrospectively analyzed Vimentin and PD-L1 expression in tumor cells and immune infiltrate to study their separate and combined effects in terms of OS." (PMID 34917615, 2021). "Several other markers such as vimentin and PDGFRβ can detect both fibroblasts and myofibroblasts in the tumor microenvironment." (PMID 34336660, 2021). "For example, EMT-related transcription factors nuclear factor kappa B (NF-κB) and Jun proto-oncogene, AP-1 transcription factor subunit (AP-1/jun) can bind to the VIM promoter and induce vimentin expression, thus promoting tumour cell migration and invasion." (PMID 33757532, 2021). "We found a weak positive correlation between PD-L1 and vimentin expressions in tumor cells as well as a correlation between the quantity of immune cells and % of immune cells PD-L1 positive." (PMID 34917615, 2021). "Vimentin is also considered as a specific marker of epithelial-mesenchymal transformation, which is closely related to tumor growth and metastasis." (PMID 33860034, 2021). "Consistent with our in vitro findings, PSD4 suppressed ethanol/DEN‐induced HCC progression along with reducing cadherin switching and vimentin expression in HCC tumor cells in vivo." (PMID 33932127, 2021). "Loss of RelA/p65 resulted in the induction of E-cadherin expression in both A549 and H1437 cells and in the suppression of N-cadherin and vimentin in A549 cells in both cells grown as tumour xenografts, or cultured as monolayers." (PMID 34503110, 2021). "ADE treatment decreased the expression of E-cadherin and increased the expression of N-cadherin and Vimentin in the primary tumor cells." (PMID 33627627, 2021). "With the employment of the Clinical Proteomic Tumor Analysis Consortium (CPTAC), the protein level of MMP9 and Vimentin were positively associated with CD44 in ccRCC tissues." (PMID 34934046, 2021). "Further, we assessed the presence of tumor microenvironment by performing immunofluorescence assay for E-cadherin and vimentin, which revealed the expression of cell adhesion molecule, E-cadherin and Vimentin in the printed NSCLC-PDX 3D spheroids." (PMID 33431915, 2021). "EMT is a critical facilitator of tumor metastasis and is characterized by upregulated expression of mesenchymal markers (e.g., N-cadherin, vimentin) and downregulated expression of epithelial markers (e.g., E-cadherin)." (PMID 34866540, 2021).
tumor (continued). "The underpinning protumourigenic USP22 on tumour cells was EMT induction, exhibiting loss of epithelial E-cadherin and gain of mesenchymal vimentin, with upregulation of MMP2/9 invasive markers in CCA cell lines." (PMID 34226501, 2021). "Meanwhile, ICG@PM@NP effectively reduced the expression of two downstream proteins related to tumor invasion (TGF-β and vimentin) in the AMPK protein pathway, thereby reducing the risk of tumor metastasis and prolonging the survival time of mice." (PMID 34794446, 2021). "Immunofluorescence of primary tumor sections also confirmed the upregulation of Vimentin and reduction in cell proliferation marker Ki67 in mice orally gavaged with milk-derived EVs." (PMID 34168137, 2021). "We previously reported that ALK-rearranged CTCs expressed a mesenchymal phenotype and high ALK protein expression in corresponding tumor tissue correlated with CK-negative areas, while tumor cells with lower CK harbored higher vimentin expression." (PMID 34272470, 2021). "The increased β-catenin at the tumor invasive front was paralleled by increased vimentin expression." (PMID 34073112, 2021). "Vimentin, expressed by interstitial cells, decreases adhesion between tumour cells, and increases their invasiveness and migration." (PMID 33757532, 2021). "In mice treated with gluconate, there was an overall decrease in the expression of PDGFRβ and vimentin particularly at the tumour–stroma interface." (PMID 33758075, 2021). "Immunohistochemistry (IHC) data indicated that KDM4A-AS1 overexpression increased Ki67, N-cadherin, and vimentin staining and decreased E-cadherin staining in xenograft tumor tissues (P < 0.05)." (PMID 34903711, 2021). "We next performed immunohistochemistry (IHC) staining for proliferation (Ki-67) and EMT (Vimentin and E-cadherin) markers on the formalin-fixed paraffin-embedded tumor tissues." (PMID 34493733, 2021). "The high expression of CBX7 and the low and high expression levels of E-cad were higher in the adjacent non-tumor tissues, whereas the low and high expression levels of VIM were lower (P < 0.05)." (PMID 33748425, 2021). "Epithelial mesenchymal-transition (EMT) is now widely recognized as an indispensable step in tumor invasion and metastasis, and E−cadherin, N−cadherin, and Vimentin are generally accepted as important molecular markers of EMT." (PMID 34956878, 2021). "E-cadherin and Vimentin as the epithelial biomarkers have been proved to play an important role in tumor metastasis." (PMID 34889158, 2021). "Epithelial‐mesenchymal transition is considered a pivotal process enabling tumor cells to metastasize, and vimentin is a mesenchymal marker upregulated during EMT." (PMID 34423578, 2021). "Hypoxia, through HIF1α stabilization, is known to induce pro-tumor phenotypes, including a collective-to-amoeboid transition in cell migration, increased in vimentin expression, and increased migration of 4T1 cells." (PMID 33859337, 2021). "IHC analysis of EMT markers in the xenograft tumor tissues confirmed increased E-cadherin and decreased Vimentin in xenograft tumors derived from miR-4521-overexpressing cells." (PMID 33407516, 2021). "Levels of mRNA encoding claudin 15 (CLDN15) and vimentin (VIM) were determined using RT‐qPCR on 483 cases to estimate the relative proportions of epithelial‐like and mesenchymal‐like components in each tumor." (PMID 32944962, 2021). "For instance, tumor metastasis is characterized by increased expression of mesenchymal-like phenotype marker vimentin, and lose of epithelial marker such as E-cadherin." (PMID 34836544, 2021).
tumor (continued). "We further verified that tumor cells co-cultured with CAFs-derived exosomes expressed lower E-cadherin and higher N-cadherin and Vimentin than that of cells co-cultured with NFs-derived exosomes." (PMID 34853307, 2021). "Immunohistochemistry analysis showed a significant increase in E-Cadherin, and reduction in MMP-2 and Vimentin level in tumor samples obtained from animals simultaneously administered Iminodibenzyl (20 mg/kg) and DGLA (5 mg) (P < 0.001)." (PMID 34535685, 2021). "In our study a positive association between the percentage of PD-L1 positive tumor cells and the percentage of vimentin in tumor cells was seen." (PMID 34917615, 2021). "Given the essential role of epithelial-mesenchymal transition (EMT) in tumor metastasis 21, we used IF to investigate the expression of vimentin and E-cadherin, two important EMT markers." (PMID 33456583, 2021). "EMT was considered as a major reason for tumor mobility which was characterized by down-regulation of epithelial markers (e.g., E-cadherin) and up-regulation of mesenchymal markers (e.g., Vimentin and N-cadherin)." (PMID 33968751, 2021). "Conversely, Seo and colleagues showed that TNBC infiltration with CD4+ and CD8+ T cells was positively correlated with the presence of CD44highCD24low tumor cells and Vimentin expression." (PMID 34063254, 2021). "Studies have shown that vimentin has become a potential target for capturing CTCs in patients with tumor." (PMID 34134721, 2021). "They confirmed ex vivo tumor cells showed increased angiogenic, proliferative and migratory features with altered mesenchymal markers including E‐cadherin, Snail, ZO‐1, and vimentin." (PMID 33599076, 2021). "Tumor cells demonstrate strong positive staining for vimentin, CD34, apolipoprotein D, and nestin when subjected to immunohistochemical studies." (PMID 33715634, 2021). "CD133 and Vimentin tumor expression were evaluated in 36 biopsies which had sufficient tumor sample for immunohistochemical analysis." (PMID 34771484, 2021). "In neoplasias of epithelial origin, vimentin serves as a biomarker of the epithelial-to-mesenchymal transition (EMT)." (PMID 33807419, 2021). "Nevertheless, in the univariate analysis, a higher vimentin expression was associated with the male gender, BRAF phenotype, and lymph node metastases, features linked to increased tumor aggressiveness." (PMID 34575184, 2021). "The results showed that the expression of Slug, N-cadherin, and vimentin was significantly decreased and that of E-cadherin, a transmembrane protein with a tumor-suppressive effect, was significantly increased." (PMID 34199353, 2021). "The results showed that the expression of VIM was significantly increased in distantly metastatic tumor tissues, while the expression of the other three genes did not change significantly." (PMID 33535187, 2021). "Dense GFAP and vimentin labeling in the brain parenchyma surrounding the tumor mass reflect the presence of reactive astrocytes." (PMID 34441246, 2021). "We detected the expression changes of E-cadherin and vimentin in tumor tissues after sufentanil treatment by qRT-PCR." (PMID 34912457, 2021). "Evidence that exposure to sorafenib leads to EMT in ACC neoplasms come from analyzing some of the markers involved in this transition, such as N-cadherin and vimentin." (PMID 34108938, 2021). "Immunohistochemically(IHC) analysis revealed that the tumour cells were positive for Desmin, Vimentin, Myo-D1 and Myogenin." (PMID 34670517, 2021). "Our preclinical data shows that citrullinated vimentin and α-enolase are promising candidate vaccine targets and as a vaccine have generated impressive anti-tumor responses in preclinical murine models." (PMID 33859638, 2021). "Vimentin expression was statistically correlated with tumor differentiation status; it was expressed in a higher proportion in poorly differentiated tumors compared with well- to moderately differentiated tumors (p = 0.0014)." (PMID 33494186, 2021).